IL10 (interleukin 10)
Diseases named in the same sentence as IL10 in open-access papers (continued):
Sharing a sentence is not in itself a finding about the gene and the disease.
infection (continued). "IL-10 is a key cytokine required for maintaining the steady-state within the healthy lung during infection where it inhibits the activity of many pro-inflammatory cells and prevents immunopathology." (PMID 32425944, 2020). "Our study showed that engagement of the TIGIT pathway limited infection-induced liver and lung damage in an IL-10-dependent manner, thus revealing a critical mechanistic aspect of TIGIT biology." (PMID 32152316, 2020). "Animals presented greater numbers of cysts than control mice, and small amounts of IFN-γ and higher IL-10 mRNA levels in the brain at week 8 of infection." (PMID 32295126, 2020). "The level of IL-10 mRNA before infection was significantly higher in the lungs of klotho KO mice than in those of klotho WT mice." (PMID 33329595, 2020). "In the case of IL-10 in CA, higher expression was induced by Nc-Spain1H infection at 10 dpi (P < 0.0001) and by both isolates at 20 dpi (P < 0.01–0.0001)." (PMID 32552750, 2020). "Elevated IL-10 characterizes chronic stages of schistosome infection and is produced by B cells starting from week 8 during infection (1.4 to 2.5-fold)." (PMID 33075079, 2020). "IL-10 has been reported to play an integral role with respect to infection, as well as inflammation, due to its anti-inflammatory effect." (PMID 32487191, 2020). "Th2 cells mainly secrete IL-4 and IL-10 and are mainly involved in humoral responses to extracellular infection." (PMID 33134305, 2020). "Peritoneal macrophages obtained of NI ccl3+/+ mice were susceptible to in vitro infection by trypomastigote forms of the Colombian strain, which triggered the production of NOx, TNF and IL-10." (PMID 32194558, 2020). "More importantly, downregulation of NHERF1 increases anti-inflammatory IL-10, a cytokine that has been shown to inhibit preterm contractions in various animal models in response to infection and inflammation." (PMID 33092043, 2020). "In this context, DC-SIGN activation by ManLAM also modulates the TLR4-mediated NFκB signaling pathway and modifies the IL-10/IL-12p70 secretion balance in favor of IL-10 to promote the infection." (PMID 32722168, 2020). "Exposure of DCs to this infection results in an increased release of IL-6 and IL-10 with STAT3 phosphorylation." (PMID 33028328, 2020). "After infection PBMΦ-0 and CBMΦ-0 both showed an increase in IL10 secretion, however, the increase was almost twice as high in PBMΦ-0." (PMID 31953452, 2020). "The antimonial drug‐resistant form of the Ld parasite (LdR) is known for increased IL‐10 production upon infection." (PMID 32031337, 2020). "Upon infection, Bregs (IL-10+ B-cells) number decreased 5-fold, significantly more than that of all B-cells or other cells in SVF." (PMID 32455939, 2020). "As L. monocytogenes infection leads to significant expression of IL-10 in both BMMs and mice four hours post-infection, we analyzed cell supernatants for IL-10 levels four hours post-infection in our screen." (PMID 32634175, 2020). "TLR2/4 plays positive roles in the induction of immune responses against Mtb and participates in eradication of the infection, while IL-10 can have deleterious effects on the patients during active TB disease in terms of bacterial clearance." (PMID 33202583, 2020). "According to previous reports, IL-10 surge is higher for infection with SbRLD as compare to sensitive counterparts." (PMID 33240825, 2020). "After 24 h of infection, increased serum (lysozyme) and skin barrier functions, down-regulation of interleukin-1beta, and upregulation of interleukin-10 were found in HI-supplemented-PBM-fed fish." (PMID 33521040, 2020). "Previous work demonstrated that infection of mice with Δhly is immunosuppressive and IL-10 levels are increased in the serum four hours post-infection, while infection with WT leads to IL-10 that peaks 3–4 days post-infection." (PMID 32634175, 2020).
infection (continued). "Serum, peritoneal fluid and saliva levels of IL-10 are known to be elevated in conditions such as infections, melanoma, tumours, and autoimmune diseases." (PMID 32487191, 2020). "This likely supports our supposition that longer time would be needed for the development of detrimental consequences of the infection with the virulent Salmonella Typhimurium, as we concluded in the case of IL-10 in the intestinal content." (PMID 31540295, 2019). "Infection of IL-10−/− mice with C. jejuni is characterized by increased levels of pro-inflammatory cytokines (TNF-α, IL-1β, IL-6, IFN-γ and IL-22) and infiltration of inflammatory cells in the colon." (PMID 31427597, 2019). "The two anti-inflammatory cytokine IL-10 and IL-4 were also produced less after infection, suggesting an overall reduction in the cytokine response during infection in AIC." (PMID 31801841, 2019). "The M. bovis strain G18, which induced prolonged expression of IL10, elicited a more silent and less cytotoxic infection than the M. bovis strain AF2122/97." (PMID 31527895, 2019). "IL-10, IL-10Rα and IL-10Rβ mutant mice were infected with a high dose of eggs and survival, tissue histopathology and worm burdens throughout infection up to day 28 p.i. were evaluated." (PMID 30640950, 2019). "Infection of AA mφ with viable bacteria led to a 7.7-fold higher level of IL-10 than inoculation with heat-killed bacteria (mean value of 317 pg/ml with standard deviation of 107 pg/ml vs. mean value of 41 pg/ml with standard deviation of 8 pg/ml)." (PMID 31134002, 2019). "Further work is required to ascertain the mechanism behind the regulation of NO production by IL10 during AF2122/97 infection." (PMID 31527895, 2019). "At 24 h, 48 h, and 72 h post-infection, significantly lower levels of IL-1Ra, IL-6, IL-8, IL-10, IL-12p40, TNF-α, MCP-1, and MIP-1b were detected in ESRD group." (PMID 31875015, 2019). "Concomitantly, RT-qPCR showed that infection of macrophages with BCG increased levels of IL-10 mRNA, which were significantly abrogated upon MK and Wort treatment in both mice and human macrophages." (PMID 31921181, 2019). "α1,3GalT-WT mice showed high levels of IFN-γ, TNF-α, and IL-10 in the early stage of infection (day 7)." (PMID 30911415, 2019). "At later stages of infection (day 21–28 p.i.), IL-10 signalling controls the type-1 driven pathology both in the caecum and the liver leading to reduced survival." (PMID 30640950, 2019). "In a small number of patients we also evaluate the expression of these cytokines after 24 h of infection and as expected there was a decrease in the intracellular expression of TNF and IL-10 as these cytokines are predominantly detected early after infection." (PMID 31119102, 2019). "MDMs infected at a Map multiplicity of 1:4 display transcription-level shifts in cytokine expression marked by upregulation of TNF-α by 15-fold by day 5 post-infection with concurrent downregulation of IL-10." (PMID 31614819, 2019). "Antibiotic and synbiotic supplementation reduced cecal tonsil IL-10 mRNA content at 21 (P < 0.01) d post-infection." (PMID 31600299, 2019). "IL10 was the predominant immuno-modulatory cytokine for the whole infection period and for both profiles." (PMID 30696429, 2019). "IL-10 possesses an essential regulatory, anti-inflammatory role but the mechanisms that lead to IL-10 production during infection and inflammation are incompletely understood." (PMID 31757102, 2019). "In murine PCM, PGE2 had an immunosuppressive effect at early steps of infection, by a mechanism dependent on IL-10 and IL-4." (PMID 31886295, 2019). "Noteworthy, A/J C5−/− mice have higher levels of TNF-α, IL-6, and IL-10 in the kidney when compared to A/J C5+/+ mice on the third day of infection." (PMID 31687410, 2019). "Two cell populations determine leishmanial condition: Th1 (IFN-γ, IL-2) in the protective condition and Th2 (IL-4, IL-10, and IL-13) in progressive infection." (PMID 30834079, 2019).
infection (continued). "After infection, the level of IL-4 in the immunized group was at a similar value than before infection, but the level of IL-10 was clearly lower than before infection." (PMID 31681308, 2019). "The presence of IL-10 secreting B cells has been reported after Schistosoma mansoni, Leishmania major, Brudia pahahgi, Listeria monocytogenes, and other pathogen infection models in mice." (PMID 30881362, 2019). "In contrast, the levels of IL-4 and IL-10 cytokines were diminished at 14 weeks post-infection in the HisAK70-immunized animals." (PMID 31739549, 2019). "Relevantly, here we show that only CD4+ and CD8+ cells from BALB/c mice showed an infection-induced increase capacity of secreting IL-10, which is retained at 8 weeks post-infection." (PMID 30881923, 2019). "In conclusion, we have furthered our understanding of the interaction of two strains of M. bovis with the infected Mø by investigating the role of IL10 during infection of bMDM." (PMID 31527895, 2019). "We suggest that a certain level of inflammation or a sequence of inflammatory processes during the infection is needed to initiate the regulatory potential of IL-10." (PMID 31950032, 2019). "Previously, we observed a higher frequency of IL-10 producing cells within MZB-like cell subpopulation and also that NOD mice showed the highest frequency of IL-10+ cells during the course of the infection." (PMID 30881362, 2019). "The complete kinetics of peripheral blood leukocytes by flow cytometry revealed that IL-10-GFP expression by NK cells starts as early as D2 with a peak observed on D4 post-infection." (PMID 31803193, 2019). "After Mtb infection, spleen lymphocytes from both BCG- and rBCG-DisA-immunized mice produced more cytokines of IFN-γ, IL-2, and IL-10 than infection control." (PMID 31333655, 2019). "Increased sytemic levels of TNF-α and IL-10 indicated the severity of infection and poor prognosis for survival in preterm infants and adults." (PMID 31434337, 2019). "In particular, the production of IL-1β and IL-6 was reduced in the groups treated with UA compared with the infection group, and the expression of IL-10 and IL-12 was significantly increased in T. gondii-infected cells treated with UA." (PMID 31075881, 2019). "Our M. bovis survival studies suggest that IL10 expression during the first 24 h of infection is important for promoting M. bovis survival in bMDM." (PMID 31527895, 2019). "While kidney levels of TNF-α, IL-6, and IL-10 were significantly increased on the third day after infection, the levels of IL-1, IL-12p40, and IL-12p70 were significantly reduced on the sixth day after infection in A/J C5−/− mice when compared to A/J C5+/+." (PMID 31687410, 2019). "Many pathogens, including viruses, bacteria and protozoa, have been shown to manipulate IL10 signalling to promote infection." (PMID 31527895, 2019). "For example, IFNG mRNA levels were on average 5.5 times higher in response to G18 infection when IL10 was knocked-down." (PMID 31527895, 2019). "At 8 weeks post-infection, expression of IL10, NOS2, and SMAD7 was significantly up-regulated in the Fe-supplemented animals." (PMID 31382404, 2019). "The cytokine array results also showed an increased level of IL-10 across conditions compared to mock infection, with the greatest level being induced by ST-17 strains." (PMID 31536604, 2019). "The results reveal that IL10 has variable effects during infection of bMDM with different M. bovis strains." (PMID 31527895, 2019). "In the present report, we provide compelling data indicating that an increased IL-10 production is observed early after the infection of the male genital tract with C. muridarum, being B cells the main source of that secretion." (PMID 30881362, 2019). "Further studies have to elucidate if re-infections of cured individuals (PI group) lead to enhanced induction of IL-10-producing immature and B10 regulatory B cells and the possible role of memory B cell activation." (PMID 31120872, 2019).
infection (continued). "The increase in TLR2 can be related to the ability to evade host defense by changing the cytokine profile produced, favoring the production of TLR2-dependent IL-10, as in infections by several other microorganisms." (PMID 31636507, 2019). "This has been confirmed by several studies investigating the effect of reducing IL10 expression during infection with MAP, M. bovis and M. tuberculosis." (PMID 31527895, 2019). "Interleukin-10 (IL-10) has long been recognized to be one of the vital anti-inflammatory cytokines, which has been unequivocally established in various models of infection, inflammation, and even cancer." (PMID 31582901, 2019). "Secondary abiotic IL-10−/− mice were infected with C. jejuni and treated with 0.5 mg/mL of curcumin, starting 4 days prior infection until the end of the observation period (i.e., day 6 post infection)." (PMID 31569415, 2019). "Taken together, our results demonstrate that the p38-MAPK signaling pathway is activated by PCV2 Rep to participate in the production of IL-10 at the later phase of infection." (PMID 31835539, 2019). "We observed that huNSG mice that were infected with 105 infectious EBV particles also had significantly higher serum levels of IFNγ, TNFα, IL-10, and IL-2 compared to infection with 103 infectious EBV particles or PBS treated huNSG animals." (PMID 31145756, 2019). "Taken together, NK cell-derived IL-10 can be critical in regulating the immune response during early phases of infection and therefore protecting the host from excessive immunopathology." (PMID 31803193, 2019). "At 12 h after the infection, interferon-gamma, interleukin-10, interleukin-17A, interleukin-1 beta, interleukin-6, and tumor necrosis factor alpha (TNF-α) tended to be suppressed with micafungin treatment in both PF and control mouse models." (PMID 31249356, 2019). "Lastly, total number of IL-10 positive NK cells was significantly higher in the liver of Gal-3 KO mice in comparison with WT mice, 36 h after infection." (PMID 30800112, 2019). "Therein the authors show an increase in the transcription levels of all the cytokines measured except for IL-10 during the first day post-infection." (PMID 30936869, 2019). "Previously we have shown that significantly more IL10 mRNA was produced by bMDM at 24–72 hpi in response to infection with G18 than AF2122/97." (PMID 31527895, 2019). "In contrast, no significant induction of expression of IL6, LITAF, and cytokine IL10 was detected after infection with the different Salmonella strains." (PMID 31998655, 2019). "IL-10 has been shown to be constitutively expressed (e.g., splenocytes), as well as in response to infection." (PMID 31100860, 2019). "Our results further confirmed that the PI3K/Akt, ERK, and p38-MAPK signaling pathways are also involved in regulating IL-10 expression at the earlier phase of infection as per our previous report." (PMID 31835539, 2019). "In this study, we investigated the immunoregulatory function of NK cells during MCMV infection and demonstrated that NK cells are major producers of IL-10 during the early stage of infection." (PMID 31803193, 2019). "The hepatic IL-10 protein levels in μMT mice were significantly lower than those of WT mice 6 weeks after infection, suggesting that B cells contribute to IL-10 production in the liver after infection." (PMID 31194740, 2019). "Again at 48 h post-infection, significantly lower levels of IL-1Ra, IL-6, IL-8, IL-10, IL-12p40, GM-CSF, TNF-α, VEGF, MCP-1, and MIP-1b were observed in the ESRD group." (PMID 31875015, 2019). "Rebounders also exhibited a higher cell infection efficacies, despite an early predominance of antiviral cytokines (IFNγ, IFNα, TNFα) over immuno-modulatory cytokines (IL10, TGFβ)." (PMID 30696429, 2019).
infection (continued). "Confirming that, strong Th1 responses were disclosed by the elevated IFN-γ/IL-10 and TNF-α/IL-10 ratios promoted by the F3 vaccine, before infection and detected in the F1 vaccinated and infected controls after challenge with L. (V.)braziliensis." (PMID 31024556, 2019). "The innate immune signature of acute UPEC UTI is reviewed elsewhere; it encompasses various cytokines, including interleukin-10 (IL-10), that is upregulated in the bladder within a few hours of experimental infection in mice." (PMID 31776239, 2019). "On the contrary, the mRNA level of the anti-inflammatory cytokine IL-10 was gradually upregulated after infection, and peaked on 7 d.p.i." (PMID 30813415, 2019). "Although GFP expression by T cells overlapped with NK cells, only a small proportion of T cells expressed IL-10 as compared to NK cells during the initial stages of infection." (PMID 31803193, 2019). "There was a significant decrease in IL-10 production by lymphocytes isolated from trained animals, mainly in animals that were trained from the 6th week of infection (IEP)." (PMID 31131262, 2019). "It has been reported that infections with CVB3 and CVB4 are associated with increased IL-10 production." (PMID 31401790, 2019). "Early sources of IL-10 during infection are macrophages or DCs, but the major source of IL-10 production in adaptive cell-mediated response is the T cells." (PMID 30849108, 2019). "Splenocytes can also produce IL-10 after the stimulus by PrpA protein of B. abortus and thus promoting the persistence of the infection." (PMID 31481953, 2019). "It is thought that elevated levels of anti-inflammatory IL-10 in early stages of infection impairs Th1 cell response and enables virus replication and spread." (PMID 31357521, 2019). "The HDAC6 gene, involved in the HDAC6/STAT3/IL10 axis, was downregulated ~3-fold later on (24 hpi) during infection in JD(–) macrophages." (PMID 31969876, 2019). "During G18 infection the expression of all investigated proinflammatory cytokines was modulated by IL10." (PMID 31527895, 2019). "Toward this goal it will also be important to further define the signaling pathways mediating NK cell IL-10 production during bacterial and other infections." (PMID 31552035, 2019). "Silveira (C. posadasii) infected mice demonstrated an increase in proinflammatory cytokine IL-1β at day 1 post infection and immunoregulatory cytokine IL-10 at day 5 post infection compared to other strains." (PMID 31572393, 2019). "In case of CL, the levels of IL4, IL8, INFγ, and MMP2 in skin biopsies and levels of TNFα, IL10, IL15, IL32γ, TGFβ, sCD26, sCD30, Cortisol, Prolactin, and SOD1 in serum, have been associated with infection and disease susceptibility." (PMID 30648003, 2019). "We observed that the ability of resting mφ and AA mφ to support chlamydial growth was not significantly affected by either pre-treatment or simultaneous treatment with IL-10 relative to the timing of infection." (PMID 31134002, 2019). "Back gating analysis further confirms that NK cells in the peripheral blood are major producer of IL-10 on D4 post infection." (PMID 31803193, 2019). "In contrast, PCLS from HDM-sensitized mice showed an attenuated antiviral response, but exaggerated IL-4, IL-6, and IL-10 secretion upon infection." (PMID 31640701, 2019). "We investigated the role of the anti-inflammatory cytokine interleukin (IL) 10 during in vitro infection of bovine monocyte-derived Mø (bMDM) with two divergent UK strains of M. bovis, which differentially modulate expression of IL10." (PMID 31527895, 2019). "Although these results seem contradictory, they support previous human and animal data, denoting increased amniotic fluid and fetal tissue levels of interleukin-10 during IA infection and/or inflammation." (PMID 31019839, 2019).